COL4A3 (collagen type IV alpha 3 chain)
Diseases named in the same sentence as COL4A3 in open-access papers (continued):
Sharing a sentence is not in itself a finding about the gene and the disease.
end stage renal disease (10 papers, 2014 to 2025). "In untreated COL4A3−/− mice (Plac), mean lifespan until death prior to end-stage renal failure (ESRF) was 66.5 ± 3.7 days." (PMID 34209341, 2021). "The average age at end-stage renal failure was the same for all mutations in COL4A5 (24.4 ±7.8 years), COL4A3 (23.3 ± 9.3) and COL4A4 (25.4 ± 10.3) (COL4A5 and COL4A3, p = 0.45; COL4A5 and COL4A4, p = 0.55; COL4A3 and COL4A4, p = 0.41)." (PMID 27627812, 2016). "Age at end-stage renal failure and severity of mutations with COL4A5, COL4A3 and COL4A4 variants." (PMID 27627812, 2016). "Mouse models of autosomal recessive AS with mutations of Col4a3 or both Col4a3 and Col4a4 genes exhibit glomerular basement membrane (GBM) lesions that mimic the human disease and present with delayed onset glomerulonephritis that progresses to end-stage renal failure (ESRF) and early death." (PMID 35743114, 2022). "Overall the mean age at onset of end-stage renal failure was not different for individuals with COL4A3 (23.2 + 9.3, years, 95% CI 20.1 to 26.5) or COL4A4 mutations (mean 25.4 ±10.3 years, 95% CI 21.3 to 29.6) compared with COL4A5 mutations (24.4 ± 7.8 years, 95% CI 23.4 to 25.4, n = 237)." (PMID 27627812, 2016). "However this study did not demonstrate any difference in the age at end-stage renal failure due to Gly substitutions with Arg, Glu or Asp compared with other substitutions for COL4A3 and COL4A4." (PMID 27627812, 2016).
IgA nephropathy (9 papers, 2020 to 2025). "By far the most diagnostic variants involve one of the three COL4A3/4/5-genes, which are the sole variants in the groups “gout”, “hereditary disorders” and “IgA nephropathy”." (PMID 36100708, 2022). "Previous studies have detected Col4A3/A4/A5 mutations in patients with familial IgA nephropathy." (PMID 37323683, 2023). "It is unclear whether severe variants predispose more often to kidney cysts or coincidental IgA glomerulonephritis which are recognized increasingly in COL4A3-, COL4A4 - and COL4A5-associated disease." (PMID 35602506, 2022). "One likely pathogenic heterozygous in-frame variant (c.3546_3548dup) was identified in the COL4A3 gene in our patient, primarily diagnosed with IgA nephropathy that was not confirmed by histopathology." (PMID 41019761, 2025). "Furthermore, in IgA nephropathy, IgAVN, and LN, we obtained consistent findings where the linear structures of COL4A3/4/5, Laminin α5β2γ1, and Integrin α3β1 were all significantly impacted, resulting in reduced protein expression." (PMID 38455522, 2024). "However, some variants in the COL4A3, COL4A4, or COL4A5 gene seem to increase the susceptibility to IgA nephropathy, which is supported by IgA deposits occasionally observed in the AS patients and the COL4A3, COL4A4, or COL4A5 gene variants reported in a minority of IgA nephropathy patients." (PMID 36699462, 2022). "We found that BMP2, COL4A3, and COL4A4 were not upregulated either in other glomerular cells in PMN or in podocytes/HRMCs in IgA nephropathy." (PMID 38785168, 2024).
deafness (8 papers, 2018 to 2025). An inherited or acquired condition characterized by the complete loss of the ability to hear from one or both ears. "For example, there were three genes which appeared to be strongly and specifically expressed in pillar cells, Col4a4 and Col4a3, which are known deafness genes, and Thsd7a, which is a gene with high variant loads in female and all participants with self-reported hearing difficulty (cluster 2K)." (PMID 35761239, 2022). "Family segregation studies and further clinical screening for COL4A3-related extra-renal symptoms, such as deafness were recommended." (PMID 38790019, 2024). "Multiple ECM genes are also upregulated in the upper-bulge compartment, including Aspn, Crispld1, Egfl6, and the deafness-related ECM genes Col4a3 and Col4a4." (PMID 30355452, 2018). "The Col4a3 KO mice exhibited signs of deafness prior to reaching 4 weeks of age." (PMID 39908276, 2025). "In the Western Romanian population studied, the risk of deafness is given by pathogenic variants in 7 genes included in the panel: GJB2, USH2A, LOXHD1, SLC26A4, USH1C, COL4A4, COL4A3, present in almost 10% of the cohort, therefore representing a significant risk." (PMID 41303398, 2025). "Four recessive (TRIOBP, SLC26A4, GJB2, COL4A3) and one dominant (SOX10) for the deafness; six recessive genes (LRGUK, DNAH9, ARMC4, DNAH2, RSPH6A, and ACE) for male infertility can be conclusively ascribed." (PMID 38884051, 2024).
glomerulosclerosis (8 papers, 2012 to 2025). A hardening of the kidney glomerulus caused by scarring of the blood vessels. "Hematoxylin and eosin (H&E) staining in the kidney sections revealed glomerular sclerosis and interstitial infiltration of mononuclear cells in Col4a3−/− mice relative to those of WT mice." (PMID 32144368, 2020). "Whereas the specific function of TGFβ in glomerulosclerosis of Col4a3–/– mice remains to be further elucidated, the contribution of TGFβ to tubulointerstitial fibrosis in autocrine or paracrine manners is clear." (PMID 31390839, 2019). "Albumin and alpha-1 globulins were decreased while creatinine, alpha-2 globulins, urine dipstick protein, leukocyte esterase (leukocytes), hemoglobin and red blood cells were all increased in both COL4A3−/− groups compared to WT, thereby confirming the presence of glomerulosclerosis." (PMID 25525413, 2014).
nephrotic syndrome (8 papers, 2005 to 2025). A collection of symptoms that include severe edema, proteinuria, and hypoalbuminemia; it is indicative of renal dysfunction. "Cases of childhood AS caused by COL4A3 presenting primarily with nephrotic syndrome (NS) are rarely reported." (PMID 39845453, 2024). "Our customized exome capture array harbored a subset of genes associated with AS and nephrotic syndrome and confirmed known or novel mutations in COL4A3, A4 or A5 in four of the five AS patients." (PMID 24130771, 2013). "With respect of the patients with compound heterozygous COL4A3 mutations, p.G333E and p.P1461L (V.1) or p.G333E and p.S1492C (V.3 and V.4), the phenotype was more severe, with an early upset of the disease, and reaching nephrotic syndrome." (PMID 29089023, 2017). "COL4A3-5 genes should be included in all steroid-resistant nephrotic syndrome genetic panels." (PMID 38780768, 2024). "In total, COL4A3 sequencing was performed in 1631 patients: in 311 as part of the nephrotic syndrome panel, in 606 as part of the FSGS panel, in 579 as part of the Alport panel, and in 135, COL4A3 sequencing was included for other suspected genetic renal diseases." (PMID 33774048, 2021). "Using this approach, we found novel or known COL4A3 or COL4A5 mutations in a subset of patients with clinically diagnosed or suspected AS, APOL1 variants associated with FSGS in African Americans and novel mutations in genes associated with nephrotic syndrome." (PMID 24130771, 2013). "COL4A3, COL4A4 and COL4A5 genes should be included in steroid-resistant nephrotic syndrome genetic panels." (PMID 38780768, 2024). "The nail-patella syndrome results from dominant autosomal mutation in the transcription factor LMX1B, which regulates genes COL4A3 and COL4A4 and the children have nephrotic syndrome and skeletal and nail dysplasia." (PMID 16878253, 2005).
glomerulonephritis (7 papers, 2014 to 2023). A renal disorder characterized by damage in the glomeruli. "In conclusion, anti-GBM glomerulonephritis is believed to be a T cell disease, and increased populations of helper T cells stimulate B cells to produce antibodies against the NC domain of Col4A3." (PMID 31689860, 2019). "Further diseases linked to PPROM were nephritis or glomerulonephritis (ACE, COL4A3, COL4A4, IGF1, NOS2, REN, TNF)." (PMID 25264875, 2014).
Kidney Cyst (7 papers, 2022 to 2025). Abnormal fluid filled sac within the kidney, either acquired or congenital. "This study clarified that kidney cysts are a more frequent occurrence in individuals with COL4A3 or COL4A4 variants than previously acknowledged and stressed the importance of considering AS in the differential diagnosis of hereditary cystic kidney diseases." (PMID 40565535, 2025). "A cystic phenotype is increasingly recognized in association with disorders caused by pathogenic variants in the COL4A3, COL4A4, and COL4A5 genes; several studies have investigated the prevalence of kidney cysts in individuals with these genetic variants." (PMID 40565535, 2025). "They conducted a study on 157 adults with pathogenic or likely pathogenic variants in the COL4A3 or COL4A4 genes and found that 53.5% had at least one kidney cyst (1+ KC) in either kidney, and 28.0% had three or more kidney cysts (3+ KCs) in either kidney." (PMID 40565535, 2025). "One explanation for the association of COL4A3, COL4A44, and COL4A5 variants with kidney cysts is that the cysts result from the distension of basement membranes weakened by disruption of the collagen IV α3α4α5 network." (PMID 40565535, 2025). "On the other hand, according to current knowledge, kidney cysts in patients with COL4A3-5 pathogenic variants are generally asymptomatic and do not require specific treatment." (PMID 38790225, 2024).
diabetes (6 papers, 2022 to 2024). "Meanwhile, in T2DM, the TYK2 promoter variant was linked to an increased incidence of diabetes and associated with dysfunctional insulin production, whereas the T allele of COL4A3 was associated with T2DM with a protective role." (PMID 38926794, 2024). "Gene expression of the myofibroblast marker α-smooth muscle actin (Acta2) and matrix molecules collagen 1 (Col1a1), collagen IV (Col4a3) and fibronectin (Fn1) were all increased 2- to 3- fold in kidneys at week 12 of diabetes." (PMID 38391050, 2024). "In conclusion, MSCs exert renal protective effects in 5/6 NPX rats, diabetic mellitus models in mice, MRL/lpr mice, COL4A3-deficient mice, UUO mice, albumin-overloaded mice, and PKD rat models by increasing levels of BMP-7, VEGF, FGFs, and HGF." (PMID 36268508, 2022). "The variant of COL4A3 may regulate the rates of production and/or turnover of other GBM components, affecting the GBM width changes in diabetes." (PMID 37587982, 2023). "Typical animal models for glomerular disease include the COL4A3 gene knockout model, 5/6 NPX (nephrectomy) model, diabetic mellitus model, and Lupus nephritis (LN) model." (PMID 36268508, 2022).
hyperphosphatemia (6 papers, 2019 to 2024). Abnormally high level of phosphate in the blood. "In summary, Col4a3−/− mice not only demonstrate hyperphosphatemia and excess FGF23 levels but also lung-associated airway pathology, including inflammation and remodeling." (PMID 36966182, 2023). "Alport (Col4a3−/−) mice are an established model of progressive CKD which develop hyperphosphatemia with severe inflammation, hypoferremia, and anemia." (PMID 35302487, 2022). "To test if hyperphosphatemia aggravates these pathologic complications, we exposed Col4a3−/− mice to a low Pi diet treatment (0.2% Pi) for 6 weeks." (PMID 35302487, 2022). "Finally, administration of a low-phosphate diet has been shown to improve skeletal muscle atrophy in Col4a3−/− mice, suggesting that in this CKD model the injury might be caused by the hyperphosphatemia." (PMID 38791164, 2024). "As models of hyperphosphatemia with CKD, we studied mice receiving an adenine-rich diet for 14 weeks and mice with deletion of Collagen 4a3 (Col4a3−/−)." (PMID 39273260, 2024). "Despite impaired kidney function and worsened hyperphosphatemia, DMP1 prevented development of LVH and improved Col4a3−/− survival." (PMID 31044094, 2019). "In the context of hyperphosphatemia, high phosphate levels, but not activated FGF23/FGFR4 signaling, seem to cause skeletal muscle atrophy, as shown in Col4a3−/− mice." (PMID 38791164, 2024). "To determine if reducing hyperphosphatemia limits skeletal muscle wasting, an important complication of CKD, we analyzed skeletal muscle from wild-type (Col4a3+/+) and Alport (Col4a3−/−) mice subjected to either a normal diet (0.6% Pi) or a low Pi diet treatment (0.2% Pi)." (PMID 35302487, 2022). "Col4a3−/− mice demonstrated impaired kidney function, reduced bone DMP1 expression, reduced bone mass, altered osteocyte morphology and connectivity, increased osteocyte apoptosis, increased serum FGF23, hyperphosphatemia, left ventricular hypertrophy (LVH), and reduced survival." (PMID 31044094, 2019).
Hypertension (6 papers, 2021 to 2025). The presence of chronic increased pressure in the systemic arterial system. "Genetic counseling following diagnosis enabled the patient’s daughter, who had longstanding isolated hematuria, to receive a diagnosis with an autosomal dominant COL4A3 mutation and initiate ARB therapy upon developing stage I hypertension." (PMID 41341327, 2025). "A prior study indicated that people with seemingly benign hematuria and TBMD might carry heterozygous mutations in the COL4A3/COL4A4 genes, raising the risks of ESRD, hypertension and proteinuria." (PMID 39830308, 2025). "However, a variable proportion of COL4A3 or COL4A4 carriers progress to proteinuria, hypertension, and ESRD, which raises the question of the nomenclature of autosomal dominant AS (ADAS)." (PMID 34212557, 2021).
Goodpasture syndrome (5 papers, 2007 to 2024). "Goodpasture’s syndrome, another progressive renal disease in which antibodies against Col4a3 attack the basement membrane, results in pulmonary manifestations including hemoptysis and pulmonary hemorrhage." (PMID 38488000, 2024). "However, Goodpasture syndrome, an autoimmune disease in which antibodies attack the basement membrane COL4A3 of lungs and kidneys, manifests lung abnormalities ranging from symptoms as mild as a dry cough and minor breathlessness to those with more severe lung damage." (PMID 27412481, 2016). "Defects in Type IV collagen genes have been shown to influence Goodpasture's syndrome, an autoimmune disease affecting the lung, and both COL4A4 and COL4A3 lie in this region, sharing a common promoter." (PMID 17903307, 2007).
asthma (4 papers, 2023 to 2025). "Serum inflammation-protective collagen 4 (COL4A3) levels are elevated in adults and children with asthma and are associated with a more severe, exacerbated allergic asthma phenotype." (PMID 37377958, 2023). "Degradation of COL4A3 is associated with the disease activity of asthma and COPD." (PMID 39143598, 2024). "A cohort study evaluating patients treated with omalizumab using an asthma control test identified COL4A3 as a novel biomarker for predicting response to anti-IgE therapy." (PMID 37377958, 2023). "COL4A3 may function differently in the chronic inflammatory tissue of asthma compared to the active airway remodeling occurring in patients with obstructive pulmonary disease." (PMID 40760731, 2025).
Basement membrane disease (4 papers, 2021 to 2025). "Based on these, a missense variant in COL4A3 (rs55703767) was associated with DKD, and COL4A3 mutations have been implicated in basement membrane diseases such as familial FSGS and Alport symport." (PMID 38926794, 2024).
cystic kidney disease (4 papers, 2025 to 2026). A congenital or acquired kidney disorder characterized by the presence of renal cysts. "Furthermore, the available evidence indicates that renal cysts can indeed be a feature in individuals harboring variants in COL4A3, COL4A4, and COL4A5." (PMID 40565535, 2025). "While ADPKD is predominantly associated with PKD1 and PKD2 gene variants, there are documented cases where individuals with pathogenic variants in COL4A3, COL4A4, or COL4A5 also present with renal cysts and even a clinical diagnosis of polycystic kidney disease (PKD)." (PMID 40565535, 2025). "Notably, COL4A3 and COL4A4 are specifically mentioned as genes to be included in cystic kidney disease panels." (PMID 40565535, 2025).
Fabry disease (4 papers, 2020 to 2024). Fabry disease (FD) is a progressive, inherited, multisystemic lysosomal storage disease characterized by specific neurological, cutaneous, renal, cardiovascular, cochleo-vestibular and cerebrovascular manifestations. "Genetic findings that modified the diagnosis in 19 patients included mutations in patients with NPHP (NPHP1 [n = 4], TTC21B [n = 3], ANKS6 [n = 1], NPHP3 [n = 1], NPHP4 [n = 1]), collagenopathies (COL4A5 [n = 7], COL4A3 [n = 1]), and Fabry disease (GLA [n = 1])." (PMID 39363361, 2024).
maturity onset diabetes (4 papers, 2018 to 2024). "Our previous study also showed that variants of the COL4A3 gene were associated with worse kidney function and heavier proteinuria in patients with maturity onset diabetes of the young." (PMID 31920969, 2019).
breast carcinoma (3 papers, 2013 to 2022). "In the current study, a significant positive association was found between higher COL4A3 expression and a favorable prognosis in breast cancer, but the exact mechanisms need further study." (PMID 35602610, 2022). "TNFSF12, TNNI3, SCG2, and COL4A3 were identified as prognostic biomarkers in breast cancer by univariate and multivariate Cox regression algorithms." (PMID 35602610, 2022).
hereditary nephritis (3 papers, 2020 to 2025). A group of inherited conditions characterized initially by hematuria and slowly progressing to renal insufficiency. "AS is a hereditary nephritis caused by the mutation of COL4A3/A4/A5 genes which encode α3/α4/α5 chains of type IV collagen." (PMID 32232700, 2020).
keratoconus (3 papers, 2009 to 2018). A degenerative, structural disorder of the eye, characterized by a cone-shaped protrusion of the cornea. "COL4A3 has already been implicated in the pathogenesis of polymorphous corneal dystrophy-3, and both genes are reported to be differentially expressed in keratoconus corneas." (PMID 20029656, 2009). "Allele frequencies and their significances in COL4A3 and COL4A4 polymorphisms between keratoconus patients and control population." (PMID 20029656, 2009). "Alterations in collagen type IV, alpha-3 (COL4A3) and collagen type IV, alpha-4 (COL4A4) genes may be responsible for a decrease in collagen types I and III, a feature often detected in keratoconus (KC)." (PMID 20029656, 2009).
lung carcinoma (3 papers, 2022 to 2023). "Col4a3 expression is associated with the poor prognosis of lung cancer patients after receiving chemotherapy, and Col8a1, Col5a3, and Col15a1 are involved in tumor growth and development." (PMID 35565312, 2022).
non-small cell lung carcinoma (3 papers, 2014 to 2024). A group of at least three distinct histological types of lung cancer, including non-small cell squamous cell carcinoma, adenocarcinoma, and large cell carcinoma. "Patients with low COL4A3 expression in non-small cell lung cancer exhibited considerably longer median survival times compared to those with high COL4A3 expression." (PMID 38907304, 2024). "High COL4A3 expression was found to correlate with poor prognosis after combined cisplatin-gemcitabine chemotherapy in non-small cell lung cancer, showing the discrepancy of biological functions of this gene in different tumors." (PMID 25105010, 2014).
sensorineural hearing loss (3 papers, 2021 to 2025). "The number of individuals with sensorineural hearing loss who had a pathogenic or likely pathogenic variant in COL4A3-5 was 29/31, and the number of individuals with ocular findings documented who had a pathogenic or likely pathogenic variant in COL4A3-5 was 5/8." (PMID 39349776, 2025).
uremia (3 papers, 2020 to 2026). A clinical syndrome associated with the retention of renal waste products or uremic toxins in the blood. "To this end, we used Col4a3-/- mice in which CKD develops progressively, as shown by the gradually decreased glomerular filtration rate and increased uremia." (PMID 41783857, 2026).